SALL2 (spalt like transcription factor 2)
Diseases named in the same sentence as SALL2 in open-access papers (continued):
Sharing a sentence is not in itself a finding about the gene and the disease.
tumor (34 papers, 2012 to 2025). "The SALL2 transcription factor has been associated with various biological processes, including organ development, neuronal differentiation, tumor suppression, cancer progression, and stemness." (PMID 33692826, 2021). "Our findings suggest a novel mechanism through CCND1/E1 promoter derepression by loss/deficiency of SALL2 tumor suppressor function." (PMID 29689621, 2018). "Together with the results showing increased tumorigenic potential of Sall2−/− cells, our studies indicate a potential mechanistic association of SALL2 deficiency with cancer, through loss of a tumor suppressor function." (PMID 29689621, 2018). "Inhibition of tumour growth in SCID mice was caused by the restoration of SALL2 expression in OC cells." (PMID 29228922, 2017). "Loss of SALL2 expression may contribute to hyperactivation of the Wnt/β-catenin pathway, thereby promoting tumor progression and influencing therapeutic responsiveness." (PMID 40869218, 2025). "SALL2 is mutated and/or downregulated in various cancers; however, its role has been investigated only in a few, such as ovarian, breast, and leukemia, confirming its tumor suppressor activity." (PMID 40869218, 2025). "Similarly, Sall2-deficient tumor organoids were more resistant to Silmitasertib-induced cell death, confirming that SALL2 sensitizes cancer cells to CK2 inhibition." (PMID 38493149, 2024). "Moreover, SALL1 and SALL2 act as tumor suppressors and are associated with proliferation arrest, ESR1 expression, and good prognosis." (PMID 34944911, 2021). "Unique within this family, SALL2 has been implicated as a possible tumor suppressor." (PMID 23029531, 2012). "This analysis showed that a subset of AXIN2 positive/SALL2-positive cells in the tumor organoids microenvironment depicts a strong positive correlation between the two genes." (PMID 40869218, 2025). "SALL2 has been characterized as a tumor suppressor in various tissues, including the ovary and breast." (PMID 40869218, 2025). "Our data described the first phosphorylation-dependent regulation of SALL2, adding new insights into the molecular mechanisms by which this tumor suppressor is downregulated in cancer cells." (PMID 38493149, 2024). "Until recently, a few studies have investigated the role of SALL2 in cancer, which acted as either an activator or repressor depending on tumor type." (PMID 39349437, 2024). "We next conducted experiments involving mouse tumor organoids to investigate the relevance of SALL2 expression on the Silmitasertib cytotoxicity in a more physiologically relevant context." (PMID 38493149, 2024). "As a member of the Sal family, Sall2 was mainly documented as either a tumor suppressor or an activator." (PMID 39349437, 2024). "Studies using mouse embryonic fibroblasts (MEFs) derived from the Sall2 knockout model suggest that SALL2/Sall2 behaves as a tumor suppressor by negatively regulating cell cycle progression and by inducing cellular apoptosis during genotoxic stress." (PMID 36438565, 2022). "In summary, SALL1 functions as a putative tumor suppressor in GBM, but SALL2 and SALL4 are crucial for tumor development and progression, which is associated with PI3K/AKT pathway activation and the maintenance of an undifferentiated aggressive phenotype." (PMID 34944911, 2021). "Here, we integrated the isoform-specific expression of SALL2 across many normal/tumor tissues with RNA seq datasets from three SALL2 isoforms (E1, E1A, short_E1A)." (PMID 33692826, 2021).
tumor (continued). "Researchers concluded that SALL2 ability to induce or suppress tumor depends on the protein and cell environment and the dominant signaling pathways." (PMID 35201439, 2021). "We here integrated current data of normal/tumor gene expression databases along with ChIP-seq binding profiles to analyze SALL2 isoforms expression distribution and infer isoform-specific SALL2 targets." (PMID 33692826, 2021). "Together, these studies suggest that SALL1 and SALL2 play opposite roles in myeloid progenitor-derived leukemia, as oncogene and tumor suppressor, respectively." (PMID 34944911, 2021). "Here we integrated current data of normal/tumor gene expression databases and spliced RNA-seq data from the ISOexpresso database along with ChIP-seq binding profiles to analyze SALL2 isoforms expression distribution and infer isoform-specific SALL2 targets." (PMID 33692826, 2021). "Some studies support a tumor suppressor role and others an oncogenic role for SALL2, which seems to depend on the cancer type." (PMID 33692826, 2021). "Silencing SALL2 in the MCF7 xenografts significantly decreased the anti‐tumor effect of tamoxifen treatment." (PMID 31657150, 2019). "5‐Aza‐dC treatment significantly increased the anti‐tumor effect of tamoxifen on tumors formed by SALL2‐hypermethylated MCF7‐TMR cells." (PMID 31657150, 2019). "Consistent with an antiproliferative function of SALL2, immortalized Sall2−/− MEFs showed enhanced growth rate, foci formation, and anchorage‐independent growth, confirming tumor suppressor properties for SALL2." (PMID 29689621, 2018). "We evaluated dCas9-MC-hu/MN-hu-targeted DNA methylation on a small CpG island in the SALL2 P2 promoter, which regulates the putative tumor suppressor gene SALL2 E1a isoform and is often silenced by hyper-methylation in ovarian cancers." (PMID 28751638, 2017). "This new data supports the tumor suppressor function of Sall2, and enhances the understanding of Sall2 role in the context of genotoxic stress." (PMID 26181197, 2015). "Several evidences indicate that the SALL2 transcription factor behaves as a tumor suppressor gene in cancer." (PMID 24040083, 2013). "p150, product of the SALL2 gene, is a binding partner of the polyoma virus large T antigen and a putative tumor suppressor." (PMID 23029531, 2012). "Together, these findings indicate the role of SALL2 as a tumor suppressor in CRC." (PMID 40869218, 2025). "We analyzed whether AXIN2 mRNA expression depends on SALL2 using non-tumor HEK293 and several CRC cell models." (PMID 40869218, 2025). "To address whether the tumor-suppressive role of SALL2 mediates cell death under treatment with Silmitasertib, we used the SW480 cells, which express SALL2 and overexpress CK2α." (PMID 38493149, 2024). "Because SALL2 has tumor suppressor activity in some cancer types, CK2 may contribute to tumorigenesis by inducing SALL2 degradation." (PMID 38493149, 2024). "In addition, SALL2 also induces cell cycle arrest and apoptosis, which further contributes to the suppression of tumor development." (PMID 37946181, 2023). "Since deregulation of cell migration promotes congenital disabilities, autoimmune syndromes, and tumor formation and spreads to other tissues, our findings suggest that the Sall2-integrin β1 axis could lead to novel therapeutic approaches." (PMID 36438565, 2022). "Since deregulation of cell migration promotes congenital abnormalities, tumor formation, and spread to other tissues, our findings suggest that the SALL2/Sall2-integrin β1 axis could be relevant for those processes." (PMID 36438565, 2022). "However, another recent bioinformatic study identified a positive correlation between SALL2 and the degree of tumor-stromal cell infiltrates in colon and rectum adenocarcinomas." (PMID 34944911, 2021). "Consistently, ERα expression was drastically reduced in SALL2‐silenced tumor cells." (PMID 31657150, 2019). "In this context, most findings suggest that SALL2 behaves as a tumor suppressor." (PMID 29689621, 2018).
tumor (continued). "SALL2 has been reported as a potential tumor suppressor in ovarian cancer and Wilms tumor." (PMID 29625565, 2018). "Tumor types were selected based on previous studies reporting deregulation of SALL2 in cancer." (PMID 29689621, 2018). "SALL2 is a putative tumour suppressor and an inactivation target of a polyoma tumour antigen." (PMID 29228922, 2017). "In addition to the effect of SALL2 on tumour growth, we studied the effect of SALL2 on tumour migration and invasion." (PMID 29228922, 2017). "Although data imply that SALL2 contributes to the growth of normal human epithelial ovarian cells, the regulatory mechanisms underlying the involvement of SALL2 in tumour growth and metastasis is not fully clear." (PMID 29228922, 2017). "SALL2 functions as a tumour suppressor to inhibit A2780 cell migration and invasion." (PMID 29228922, 2017). "The molecular function of the SALL2 protein is largely unknown, although a role as a tumor suppressor has been suggested." (PMID 24412933, 2014). "Moreover, supporting a tumor suppressor function, the immortalized Sall2−/− MEFs showed an enhanced growth rate, foci formation, and anchorage-independent growth in comparison to the immortalized Sall2+/+ MEFs." (PMID 34944911, 2021). "Thus, SALL2 regulation is vital for suppression of tumour growth." (PMID 29228922, 2017). "Previous analyses of public datasets have shown a significant downregulation of SALL2 mRNA expression in CRC samples compared to normal tissues, suggesting that its tumor suppressor activity is involved in colon carcinogenesis." (PMID 40869218, 2025). "Spalt-like transcription factor 2 (SALL2), a member of the Cys2His2-like fold group (C2H2) zinc finger transcription factor family plays an essential role in cell growth and tumor progression." (PMID 35201439, 2021). "In oral squamous cell carcinoma (OSCC), SALL2 promoter hypermethylation positively correlates with SALL1 and SALL3 promoter methylation status and aggressive tumor behavior." (PMID 34944911, 2021). "It was described that POU3F2, SOX2, SALL2, and OLIG2 maintain the tumor-forming capability of these cells." (PMID 32634135, 2020). "However, the relationship between SALL2 and CRC, the role of the human ortholog in the Wnt/β-catenin pathway, and its influence on tumor progression and CRC molecular features remain unexplored." (PMID 40869218, 2025). "Given that CK2 is overexpressed in cancer and exerts protumoral effects by downregulating tumor suppressors, we assessed whether pharmacological inhibition of CK2 via Silmitasertib increases endogenous SALL2 protein levels in different cancer cell lines." (PMID 38493149, 2024). "The identified CK2-SALL2 axis may be part of a broader mechanism where CK2 downregulates the stability of multiple tumor suppressors in the cell, including iκB, VHL, PML, and SALL2, by phosphorylating residues near or within PEST motifs." (PMID 38493149, 2024). "Most cancer studies relate SALL4 to an oncogenic function and SALL1–3 to a tumor suppression role; still, there is evidence that SALL1 and SALL2 could play a dual role." (PMID 34944911, 2021). "SALL2 and SALL4 are positive regulators of PTEN and can regulate tumor metastasis." (PMID 32707933, 2020). "SALL2 and SALL4 have been recently recognized as regulators of tumorigenesis, but little information is known about the role of the SALL1 gene in regulation of tumor biology." (PMID 29625565, 2018). "Considering that Sall2−/− MEFs displayed transformation properties and data from R2 platform show a negative correlation between SALL2 and G1‐S cyclins mRNA expression in various cancers, our studies further support a tumor suppressor role for SALL2." (PMID 29689621, 2018).
tumor (continued). "Not in complete agreement with this hypothesis is that SALL2 is found upregulated in various human cancers, and that Sall2 knockout mouse models that currently exits do not show spontaneous tumor formation." (PMID 24040083, 2013). "Heatmap analysis of gene expression in adherent cells and stem‐like tumor spheres revealed a negative correlation between YY2 and stem‐related factors, including CD44, SOX9, SALL2, KLF15, OCT4 (also known as POU class 5 homeobox 1 or POU5F1), MYC, ASCL1, and POU3F2." (PMID 37300334, 2023).
cancer (26 papers, 2012 to 2025). A tumor composed of atypical neoplastic, often pleomorphic cells that invade other tissues. "Promoter methylation, histone acetylation, and loss of heterozygosity account for epigenetic mechanisms and chromosomal events underlying the downregulation of SALL2 in cancer." (PMID 38493149, 2024). "SALL2/Sall2 is a transcription factor associated with development, neuronal differentiation, and cancer." (PMID 36438565, 2022). "In disease, SALL2 is associated with eye, kidney, and brain disorders, but mainly is related to cancer." (PMID 33692826, 2021). "Altogether, these results indicate that ER loss is required for SALL2 silencing‐induced estrogen‐independent growth and tamoxifen‐resistant phenotype of ER‐positive cancer cells." (PMID 31657150, 2019). "Previous studies have reported that serum deprivation induces SALL2 expression and that highly proliferative cancer cells usually create local hypoxia and nutrient deficiencies." (PMID 31657150, 2019). "Promoter methylation‐mediated loss of SALL2 conferred an estrogen‐independent and tamoxifen‐resistant phenotype to ERα‐positive cancer cells via ERα downregulation and Akt/mTOR signaling activation." (PMID 31657150, 2019). "Interesting for cancer research, it is the fact that Sall2 deficiency increases the growth rate, foci formation, and ability of immortalized MEFs to form colonies in soft agar, similar to the effect of knocking out ATF3, an inhibitor of cyclin D1." (PMID 29689621, 2018). "Since SALL2 is a transcription factor, deregulation of its expression should affect gene expression, thereby explaining its association with cancer." (PMID 24040083, 2013). "SALL2, a zinc finger transcription factor deregulated in various cancers, has been implicated in Wnt signaling regulation through its Xenopus ortholog; however, its role in human CRC remains unclear." (PMID 40869218, 2025). "Additionally, we conducted a differential expression analysis to investigate the association between SALL2 and the Wnt pathway-related genes in cancer." (PMID 40869218, 2025). "Specifically, cancers with SALL2 mutations displayed upregulated WNT7B and downregulated AXIN2." (PMID 40869218, 2025). "Concerning SALL2 (spalt-like transcription factor 2), which is a member of the spalt/sal family of transcription factors associated with cell differentiation, development, and stemness, its expression in cancer is still controversial." (PMID 36428851, 2022). "Interestingly, two reports contradict this conclusion, associating SALL2 deficiency with increased cell migration in cancer." (PMID 36438565, 2022). "Herein, we found that SALL2 was significantly downregulated during tamoxifen therapy, and loss of SALL2 conferred estrogen‐independent growth and tamoxifen‐resistant phenotype in ER+ cancer cells by decreasing ERα and PTEN expression." (PMID 31657150, 2019). "Importantly, SALL2 is deregulated and/or mutated in various cancers, suggesting a role for SALL2 in the disease." (PMID 29689621, 2018). "Evidences for Sall2 association with cancer are increasing, but are still controversial." (PMID 26181197, 2015). "However, in some cancer cells, SALL2 deficiency is associated with increased cell migration." (PMID 36438565, 2022). "In addition, SALL2 deregulation has been associated with cancer." (PMID 34830820, 2021). "Therefore, how SALL2 is associated with cancer is controversial." (PMID 29689621, 2018). "We focused on the SALL2 E1A isoform because it exhibits the most significant overall change in expression levels in cancer." (PMID 40869218, 2025). "IHC analysis using QuPath software revealed that 40.3% of cytokeratin-positive cells in normal tissue were also SALL2-positive, compared to just 7.5% in cancer tissue." (PMID 40869218, 2025). "Given the essential role of the stroma in both normal colon epithelium and cancer progression, further investigation into the function of the SALL2 transcription factor in stromal cells is necessary." (PMID 40869218, 2025).